TSLP (thymic stromal lymphopoietin)
Diseases named in the same sentence as TSLP in open-access papers (continued):
Sharing a sentence is not in itself a finding about the gene and the disease.
asthma (continued). "Furthermore, the recently discovered innate lymphoid cells (ILC) type 2 seem to play a major role in allergic eosinophilic asthma as they secrete asthma-associated cytokines such as IL-13 and IL-5 in response to the epithelia derived cytokines IL-25, IL-33, and thymic stromal lymphopoietin (TSLP)." (PMID 27468754, 2016). "More recently, a genome-wide association study in a Japanese population-based cohort of adult asthma utilizing fine mapping analysis of the region on chromosome 5q22 using 13 tag SNPs showed that rs1837253 represented an associated LD block spanning 88 kb that included two genes, TSLP and WDR36." (PMID 22973903, 2012). "Similarly, Liu and colleagues demonstrated that one particular variant of TSLP (rs1898671) contributed to asthma susceptibility in admixed urban populations and that the risk of asthma was significantly increased in ex-smokers; suggesting gene and environment interaction." (PMID 22973903, 2012). "Therefore, outbred K14-TSLPtg mice constituted a suitable model in which to examine whether epidermal TSLP overexpression alone would increase susceptibility to asthma upon allergen exposure." (PMID 19557146, 2009). "Thus, the potentially high systemic availability of skin-derived TSLP and its central role in promoting asthma bring up the possibility that TSLP may be the factor predisposing AD patients to asthma." (PMID 19557146, 2009). "This case report describes asthma patient cases with uncontrolled T2 inflammation on tezepelumab and explores the potential evasion mechanisms of TSLP blockage." (PMID 42032643, 2026). "This systematic review synthesised and evaluated the quality of evidence on predictors of response to anti‐IL5/5Rα, 4Rα, and anti‐TSLP for severe asthma." (PMID 40956008, 2026). "The findings regarding TSLP and human asthma align with the mouse model, as TSLP promotes the proliferation of CD4+ T cells and enhances Type 2 cytokine production." (PMID 41568067, 2026). "This systematic review is the first comprehensive synthesis of evidence on predictors of response to anti‐IL5/5Rα, −4Rα, and anti‐TSLP therapies for severe asthma." (PMID 40956008, 2026). "Dupilumab attenuated the expression of both TSLP and IL-8 induced by co-stimulation with dsRNA and IL-4/IL-13 in HSAECs, suggesting its potential therapeutic benefit in virus-induced asthma exacerbations, particularly in type 2 asthma." (PMID 41576028, 2026). "Specifically, IL-37 can alleviate asthma by inhibiting Th2/Th17 immune responses, inhibiting the release of epithelial-derived alarmins (TSLP and IL-33), and attenuating airway remodeling." (PMID 41293155, 2025). "The potential of anti-TSLP therapy to induce remission in asthma is a new and promising field of research, particularly in resistant and severe asthma." (PMID 40283665, 2025). "In line with this, treatment with anti-TSLP monoclonal antibodies reduces blood eosinophil counts and airway submucosal tissue eosinophil numbers in patients with asthma." (PMID 40919679, 2025). "TSLP expression correlates with asthma severity and has also been detected in COPD airways, suggesting that it is involved in the development of airway inflammation." (PMID 41259396, 2025). "TSLPR deficiency reduced airway hyperresponsiveness but did not significantly impact lung eosinophil and neutrophil counts or mucus and collagen production in a chronic HDM asthma model, highlighting the complex role of TSLP and TSLPR in severe asthma." (PMID 41259396, 2025). "Tezepelumab, a mAb specific for thymic stromal lymphopoietin, reduced clinically significant asthma exacerbations and symptom severity in patients with severe asthma patients." (PMID 41440490, 2025). "This convergence of murine and human data highlights the potential of TSLP as both a therapeutic target and a biomarker for monitoring asthma remission." (PMID 40503233, 2025).
asthma (continued). "PF-07275315 (Tilrekimig) is a trispecific antibody targeting TSLP, IL-4, and IL-13 currently in phase 2 clinical development for the treatment of asthma (NCT06977581) and atopic dermatitis (NCT05995964)." (PMID 41409758, 2025). "Secondary endpoints of trials of the anti-TSLP Tezepelumab examined outcomes in T2-high vs. T2-low groups and found benefits across asthma endotypes defined in part by serum IgE levels > 100 IU/mL (T2 high) or < 100 IU/mL (T2 low)." (PMID 40863432, 2025). "All seven studies measuring TSLP in bronchial biopsy specimens, and all six studies analyzing TSLP in BALf and bronchial brushings reported higher TSLP expression in patients with asthma compared with healthy controls." (PMID 41357156, 2025). "While our study provides novel insights into the role of TSLP in asthma remission, we acknowledge several limitations that warrant further investigation." (PMID 40503233, 2025). "In the case of paucigranulocytic asthma, TSLP-mediated cross-reactions occur between mast cells and the building cells of the respiratory tract, i.e., fibroblasts, smooth muscle cells, or epithelial cells." (PMID 40723867, 2025). "Through activation of Th2 and other inflammatory pathways, TSLP has been demonstrated to play important roles in driving disease pathogenesis in inflammatory diseases such as asthma and COPD." (PMID 41409758, 2025). "In patients with asthma, elevated TSLP expression has been reported in the bronchial mucosa compared with that in healthy individuals, and high TSLP levels have been correlated with increased asthma severity." (PMID 41145900, 2025). "Asthma airway hyperresponsiveness correlates with airway TSLP levels, and inhibition of TSLP with tezepelumab has proven to be an effective therapy in patients with asthma." (PMID 41409758, 2025). "Consistent with the importance of these mediators in asthma pathophysiology, approved biologic therapies for severe asthma target IgE, IL-4, IL-5, or thymic stromal lymphopoietin." (PMID 41458996, 2025). "ROC curves analysis was further conducted to validate serum TSLP level correlated with clinical remission in Th2-high asthma (AUC=0.5887, 95% CI: 0.5052 to 0.7038, P <0.05)." (PMID 40503233, 2025). "When the subgroups of patients were analyzed, a correlation between TSLPR and TSLP expression in polyp samples was observed in the CRSwNP (r = 0.664; p = 0.026) and CRSwNP with asthma subgroups (r = 0.692; p = 0.018)." (PMID 39940994, 2025). "Most studies reported higher blood TSLP concentration in asthma patients compared with healthy controls, while results in airway specimens were diverse." (PMID 41357156, 2025). "Serum and tissue levels of TSLP are elevated in patients with asthma and COPD compared with healthy controls." (PMID 41409758, 2025). "Ecleralimab (anti-TSLP) is a novel inhaled anti-TSLP that in a phase IIa proof-of-concept study, was well tolerated and reduced allergen-induced bronchoconstriction in adults with mild asthma." (PMID 40364184, 2025). "A personalized medicine approach to treating patients with severe asthma has been made possible by the introduction of several biological immunotherapies (e.g., anti-TSLP, anti-IgE)." (PMID 40746413, 2025). "In this regard, the fully human anti-TSLP monoclonal antibody tezepelumab has been developed and approved as anti-asthma biologic therapy." (PMID 41321706, 2025). "As a consequence, these findings underscore the crucial role played by TSLP within the intercellular axis connecting airway inflammatory and structural cells, which significantly contributes to bronchial remodeling in asthma." (PMID 41321706, 2025). "GSK5784283 is a humanized anti-TSLP monoclonal antibody modified for extended half-life currently in phase 2 development in asthma (NCT06748053)." (PMID 41409758, 2025).
asthma (continued). "We report for the first time that serum TSLP can be used as one of the biomarkers to evaluate the remission of asthma, along with other measurements such as lung function and IgE to improve the accuracy." (PMID 40503233, 2025). "Of the asthma-associated loci, 26/87 were GWS associated with CRSwNP, including three (5q22.1, 6p21, and 9p24.1, near genes TSLP, HLA, and IL33, respectively) associated with CRSsNP as well." (PMID 41213931, 2025). "Although our literature search did not identify any data regarding TSLP’s role in remodeling in CRSwNP specifically, TSLP is known to influence airway remodeling in asthma and in NEC cultures from patients with AR." (PMID 40919679, 2025). "Key triggers for mast cell activation in asthma include allergen-stimulated IgE receptors (FCεRI), toll-like receptors, and cytokines that activate alarmin receptors (e.g., TSLP, IL-33)." (PMID 40443529, 2025). "By inhibiting TSLP, tezepelumab addresses an upstream component in the inflammatory pathway of asthma, offering a novel therapeutic option for patients with severe asthma." (PMID 40149651, 2025). "In severe asthma, Tezepelumab, a monoclonal antibody targeting thymic stromal lymphopoietin (TSLP) reduces exacerbations and improves lung function and quality of life across phenotypes, including those with low eosinophil counts or nonallergic disease." (PMID 41234678, 2025). "Although the role of TSLP in asthma has been well described, the role of TSLP in CRSwNP has yet to be comprehensively outlined." (PMID 40919679, 2025). "Second, asthma endotypes are not dominated by Th2 inflammation other endotypes such as Th2-low, neutrophilic, and Th17-high asthma, likely have different biomarker profiles and TSLP-driven pathways." (PMID 40503233, 2025). "Future studies should stratify or adjust for such co-morbidities to isolate the asthma-specific contribution to serum TSLP." (PMID 40503233, 2025). "Tezepelumab, a monoclonal antibody directed against TSLP, is approved for the treatment of patients with moderate-to-severe asthma and is in development for other type 2 inflammatory diseases." (PMID 41409758, 2025). "Type 2 immune responses in asthma are initiated by master regulatory cytokines called alarmins which include IL‐33 and thymic stromal lymphopoietin (TSLP)." (PMID 40105091, 2025). "Anti-TSLP therapy appears quite effective in severe asthma and is currently in clinical trials but there remains the potential for interference with the homeostatic actions of short TSLP in the intestine or other tissues." (PMID 40426880, 2025). "Tezepelumab, a clinical human monoclonal antibody binding to TSLP, is used to treat severe asthma via subcutaneous injection." (PMID 41211661, 2025). "Levels of TSLP are increased in patients with asthma, while higher concentrations were correlated with a more severe condition." (PMID 40723867, 2025). "Lunsekimig is a bispecific NANOBODY® that blocks both TSLP and IL-13 signaling in development for asthma and COPD." (PMID 41409758, 2025). "Cigarette smoke, a well-known aggravator of asthma, has been demonstrated to increase TSLP secretion from bronchial epithelial cells." (PMID 39962262, 2025). "Airway epithelial cells from donors with asthma have been shown to produce elevated proinflammatory alarmin cytokine expression, including thymic stromal lymphopoietin (TSLP)." (PMID 40745660, 2025). "Preclinical data presented at ATS 2025 demonstrated that HXN-1011 induced greater inhibition of inflammatory cytokine expression compared with a benchmark anti-TSLP antibody in a mouse model of asthma." (PMID 41409758, 2025). "In contrast, increased levels of IL‐13, TSLP and sST2 were found in females with asthma compared with males." (PMID 40022441, 2025). "When looking at the data coming from asthma trials, the broader action of tezepelumab, an anti‐TSLP agent, has the potential to fully address the major drivers and clinical expressions of ABPA pathobiology, including mucus plugging." (PMID 40751367, 2025).
asthma (continued). "To further validate these findings, we employed a mouse model of asthma progression, demonstrating TSLP upregulation in chronic asthma and attenuation during remission." (PMID 40503233, 2025). "BL IL‐33 levels were equal in all groups, but within the asthma group, TSLP levels were higher in females compared to males (p < 0.0001)." (PMID 40022441, 2025). "In asthma, TSLP is a key alarmin which enhances Type‐2 immunity progression of allergic disease and alterations resulting in airway remodeling." (PMID 40751367, 2025). "To date, the anti-TSLP monoclonal antibody tezepelumab has shown clinical efficacy in both type-2 high and type-2 low asthma by modulating the upstream cytokine pathways involved in asthma pathogenesis." (PMID 40313547, 2025). "With regard to the pathobiology of T2-high asthma, a further contribution of TSLP refers to its property of inducing the differentiation of alternatively activated M2 macrophages, which are associated with allergic inflammation." (PMID 41321706, 2025). "Tezepelumab is a humanized monoclonal antibody against TSLP to prevent asthma exacerbations and improve asthma control." (PMID 40520782, 2025). "By targeting immunoglobulin E (IgE), thymic stromal lymphopoietin (TSLP), and specific cytokines such as IL-5, IL-4, and IL-13, biologics offer more precise and personalized treatment in patients with severe asthma and associated comorbidities." (PMID 41156259, 2025). "This is in line with our observation of significant increases in TSLP, IL-33, and IL-25 protein levels following T2 stimulation and viral infection, specifically in asthma-derived BECs." (PMID 40370530, 2025). "Clinically, elevated TSLP levels in bronchoalveolar lavage fluid and airway tissues correlate with disease severity and airway obstruction in children with asthma." (PMID 41169790, 2025). "In T2-high asthma, goblet cell metaplasia and epigenetic activation of alarmin (IL-25, IL-33, and TSLP) and Th2-related loci are prominent." (PMID 40806756, 2025). "Tezepelumab is the first monoclonal antibody blocking the biological activity of TSLP approved for patients with T2-high or T2-low phenotype of severe asthma, whereas all previously approved biological agents are indicated only for T2-high asthma." (PMID 41357156, 2025). "In this regard, lunsekimig (also known as SAR443765), a bispecific nanobody-based molecule targeting both TSLP and IL-13, is being evaluated in Phase II trials for asthma." (PMID 41294800, 2025). "Instead, a potential involvement of the TSLP and IL-33 in asthma vascular remodeling emerged from interesting findings in the correlation analyses." (PMID 40022191, 2025). "TSLP plays a critical role in various diseases, including asthma, atopic dermatitis, inflammatory bowel disease, coronary artery disease, and certain cancers." (PMID 40787610, 2025). "Conversely, the anti‐TSLP tezepelumab has proven effective in the treatment of severe asthma but has shown limited efficacy in atopic dermatitis." (PMID 40662227, 2025). "This study analyzed the clinical and biomarker data from 175 adults with severe asthma treated with the anti‐TSLP monoclonal antibody tezepelumab." (PMID 40365686, 2025). "The recent approval of an anti-TSLP mAb for asthma treatment also emphasizes the urgent need for additional research on the role of TSLP, a Janus cytokine, in tumorigenesis." (PMID 40873585, 2025). "Specifically, in a murine asthma model study, IL-33 induced angiogenesis and vascular permeability, while TSLP contributed to the release of VEGF-A from human lung macrophage." (PMID 40022191, 2025). "TSLP is effectively bound and sequestered by tezepelumab, which can be usefully utilized across T2-high and T2-low asthma phenotypes/endotypes." (PMID 41321706, 2025). "In children with asthma, TSLP, IL-25 and IL-33 are recognized as key epithelial mediators that define the T2-high endotype and have been highlighted as potential therapeutic targets and biomarkers of disease activity." (PMID 40981017, 2025).
asthma (continued). "Compared to the efficacy in enhancing lung function and controlling asthma in asthma patients, TSLP monoclonal antibodies in treating skin lesions in AD are limited." (PMID 40443683, 2025). "The clinical trials with tezepelumab (monoclonal anti-TSLP) showed the potential for improving sinonasal symptoms of severe asthma comorbid with CRSwNP." (PMID 40292285, 2025). "Among these genes, target for TSLP is licensed for severe asthma and in the clinical phase for CRSwNP." (PMID 40098143, 2025). "In a TSLP/OVA-induced asthma model with transgenic human TSLP, TSLP receptor, IL-4, and IL-4Rα mice, the BsAb reduced every single allergic/inflammatory hallmark, while the single target blockade antibody failed to have such comprehensive effects." (PMID 41294800, 2025). "For instance, bispecific monoclonal antibodies like IBI 3002 (targeting IL-4Rα and TSLP) and lunsekimig (targeting TSLP and IL-13) aim to address both T2 and non-T2 inflammation in asthma." (PMID 40004611, 2025). "While TSLP has been extensively studied in asthma, unresolved research gaps and substantial variability across studies limit the strength of current conclusions." (PMID 41357156, 2025). "In support of this, prior studies have demonstrated the synergistic role of TSLP alongside other Th2 inflammation markers, such as Periostin and blood eosinophil counts, in stratifying asthma severity and predicting treatment response." (PMID 40503233, 2025). "Tezepelumab, an anti‐thymic stromal lymphopoietin antibody, reduces exacerbations and improves lung function in severe asthma." (PMID 41234678, 2025). "In the group of patients with asthma exacerbation, TSLP levels decreased following OCS treatment in the steroid responders' group; however, in the group of paradoxical responders, TSLP levels did not decrease after OCS treatment during asthma exacerbation." (PMID 41357156, 2025). "IL-4 and RV infection induced a significant increase in thymic stromal lymphopoietin (TSLP) levels in BECs from asthma compared with healthy, which was normalized by IL-4Rα mAb." (PMID 40370530, 2025). "It is clearly that the epithelial and epidermal derived alarmins IL-25, IL-33, and TSLP play crucial roles in the action of allergic inflammation in asthma and AD." (PMID 40236701, 2025). "Macrolides have historically been used to fill a therapeutic gap in T2-low asthma, but the advent of tezepelumab—a Thymic Stromal Lymphopoietin (TSLP)-blocking biologic—has shifted this landscape." (PMID 41301557, 2025). "The commonality of the action of anti-TSLP and anti-IL-5 treatment in preventing eosinophilic inflammation also provides the rationale for combination therapy in enhancing severe asthma outcomes." (PMID 40283665, 2025). "In an acute OVA model of asthma in TSLP/TSLPR humanized mice, TAVO101 reduces total serum IgE, lung TARC, IL-13, and eosinophil accumulation similarly to a benchmark anti-TSLP." (PMID 41409758, 2025). "Thymic stromal lymphopoietin (TSLP), a cytokine produced by epithelial cells, plays a critical upstream role in the development of asthma." (PMID 40660066, 2025). "In contrast to T2-high asthma, epithelial-derived alarmins such as IL-33, IL-25, and TSLP play a less prominent role in T2-low asthma." (PMID 40806756, 2025). "The synergy of dual inhibition of TSLP and IL-4Rα was also evident phenotypically in the humanized mouse asthma model." (PMID 41294800, 2025). "In severe asthma, TSLP is referred to as a molecule that plays the most important role in triggering the cascade of the inflammatory response." (PMID 40723867, 2025). "TSLP plays a critical role in various diseases, including asthma, atopic dermatitis, inflammatory bowel diseases, coronary artery disease, and certain cancers." (PMID 40787610, 2025).